FOXP3 (forkhead box P3)
Diseases named in the same sentence as FOXP3 in open-access papers (continued):
Sharing a sentence is not in itself a finding about the gene and the disease.
Autoimmunity (continued). "Foxp3, a 47-kDa transcription factor, is necessary for the function of CD4+CD25+ regulatory T cells (Tregs), with an essential role in the control of self-reactive T cells and in preventing autoimmunity." (PMID 19924293, 2009). "In mice, a Foxp3 conditional knock out of Icos (Foxp3YFP-CREIcosfl/fl) does not generate autoimmunity, but rather prevents tissue-localised TREG cells from suppressing oxalone-induced dermatitis, suggesting Icos is particularly required for TREG cells to control tissue injury." (PMID 38605970, 2024). "We observed no clear signs of frank autoimmunity in aged (1-year-old) Ikzf1-fl-Foxp3-YFP-Cre mice." (PMID 38655862, 2024). "CD4+ Tregs expressing the transcription factor Foxp3 is required for peripheral immunological tolerance (regulation of autoreactive immune cells); deletion of Foxp3 on CD4+ regulatory cells leads to multiorgan autoimmunity and malfunction of Tregs are related to the alteration of the Foxp3 gene." (PMID 38213874, 2024). "Similarly, ASO FOXP3 treated mice in TC1 model had no apparent histologic evidences of autoimmunity or inflammation in their tissues, which was supported by an absence of CD25 upregulation in non-Treg subsets." (PMID 39234236, 2024). "These CD4+Foxp3+ Treg cells can modulate the balance and stability of the immune system within the body by regulating the timing and magnitude of immune responses, not just to autoimmunity but also to other antigens." (PMID 37795866, 2023). "The transcription factor Foxp3 is known for its role as a master regulator of regulatory T cell (Treg) function, a dynamic subgroup of CD4+ T lymphocytes that modulate the response of the immune system under physiological and pathological conditions, such as autoimmunity and cancer." (PMID 37766222, 2023). "The importance of Treg cells has been demonstrated in murine models—depletion of Foxp3+CD4+ Treg cells resulted in severe autoimmunity, allergy, and immunopathology (e.g., IPEX) in otherwise normal animals and those same diseases can be prevented by reconstituting Treg cells." (PMID 35207219, 2022). "The etiology of autoimmunity and lymphoproliferation in AMPK-KO mice might be multifactorial, but we provided evidence that Tregs from these mice exhibited functional instability due to increased Foxp3+CD25− Treg population." (PMID 36293240, 2022). "Thus, Foxp3 modifies the gene expression dynamics of TCR-induced genes, which constitute cardinal mechanisms for Treg-mediated immune suppression and related self-tolerance and prevention of autoimmunity." (PMID 35935991, 2022). "This defensive activity was first identified in mice lacking thymic-derived CD4+CD25hiForkhead box P3 (FOXP3)+ Treg cells and in Treg-depleted animals which develop a constellation of autoimmune conditions including thyroiditis, diabetes, autoimmune gastritis, and inflammatory bowel disease." (PMID 34489935, 2021). "On the other hand, co-expression of Tbet with Foxp3 is essential for Treg cells to control Th1 responses, as the depletion of Tbet-expressing Treg cells -but not of Tbet expression in Treg cells-results in severe Th1 autoimmunity." (PMID 31188899, 2019). "This outcome is analogous to that seen when we deleted both CBP and p300 within Foxp3+ Tregs, deletion of either HAT alone had only modest effects on Treg suppressive function, whereas dual deletion, like in the current study, led to death from overwhelming autoimmunity by 3–4 weeks of life." (PMID 31003455, 2019). "However, recent research has suggested that the modulation of the Foxp3+ regulatory T-cells (Tregs) and the use of cytokine therapy with IL-2 (NCT02772679) may partially prevent ßeta-cell autoimmunity." (PMID 30794611, 2019). "Similarly, scurfy mice, lacking a functional Foxp3 gene, display a profoundly dysregulated immune system, including severe generalised autoimmunity, and die of uncontrolled lymphoproliferative disease." (PMID 28770318, 2017).
Autoimmunity (continued). "Thus, we demonstrated that GAG ameliorated autoimmune T1DM by upregulating both CD4+FoxP3+ and CD8+CD122+PD-1+ Tregs while GAG synergized with CsA to further suppress autoimmunity and T1DM by reversing the decline in CD4+FoxP3+ Tregs resulted from CsA treatments." (PMID 28947964, 2017). "Of interest, frequencies of insulin mimetope-specific Foxp3+Tregs were significantly lower in children with recent onset of autoimmunity than in children without autoimmunity (no autoimmunity versus recent onset of autoimmunity: 1.9±0.9 versus 0.5±0.4% of Tet+CD4+T cells, P<0.05)." (PMID 26975663, 2016). "The identification of forkhead box P3 (FOX P3) as a critical determinant of CD4(+) CD25(+) T(REG) cell development and function has provided insights into the delicate balance between autoreactive and regulatory mechanisms in autoimmune disorders including chronic autoimmune urticaria." (PMID 25120565, 2014). "Second, and in contrast, adoptive transfer of CD4+Foxp3+CD25+ Treg-delayed disease progression and significantly reduced mortality in mice with already established disease, indicating that, depending on a sufficient amount, Treg are able to counteract even chronically active autoimmunity." (PMID 23446139, 2013). "Additional analysis of that FoxP3+ T cell population in Roquinsan/san mice may provide insight into how Roquin controls or fails to control autoimmunity." (PMID 23451046, 2013). "However, autoimmunity in other immunodeficiencies, such as ADA-SCID and WAS, has been recently associated with altered function of Treg cells, regardless of FOXP3 expression." (PMID 23060872, 2012). "Recent observations also suggest that TGF-β induces Foxp3 expression and differentiation of adoptive populations of Treg cells in peripheral tissues and GALT, in particular, and in excessive levels TGF-β can expand Tregs to protect against autoimmunity as it was demonstrated in diabetic NOD mice." (PMID 20126401, 2010). "Similarly, other genes including NOD2 and FOXP3 are regarded as master switches of autoimmunity, and these genes were not included in this study." (PMID 19180256, 2009). "Since the point of control over immune reactivity occurs at IL2 gene expression, it is logical that defects in the IL2/FOXP3 negative feedback loop may lead to a preponderance of activating signals and autoimmunity." (PMID 18324310, 2008). "To determine whether the expression of FoxP3 prevents RORγt+-expressing cells to produce IL-17 in SorA-treated cells, we made use of Scurfy × Ox40/CD30ko mice, a genetic mouse model devoid of Tregs but without lethal autoimmunity or activated T cells." (PMID 39929287, 2025). "Given that the endogenous Foxp3 gene and the Foxp3BAC-DTR/GFP transgene are not physically linked, the activity of Foxp3+ Treg cells with a DTR/GFP– phenotype may represent another mechanism that limits catastrophic autoimmunity in DT-treated NOD.DEREG mice." (PMID 34447385, 2021). "Since FOXP3 mRNA directly correlated with post-transplantation time the authors speculated that FOXP3 positive cells possessed the key to control the potential for autoimmunity in these sites rather than representing a cognate immune-response." (PMID 21992116, 2011). "Positive correlations were observed between the intrahepatic expression levels of Foxp3 with the expression of Fas (P = .014), FasL (P < .001) and TRAIL (P = .003), Fas and TRAIL (P < .001), and FasL and IFN-γ (P < .001), irrespective of the cause of liver damage (viral, NAFLD, autoimmunity, MTX)." (PMID 21772667, 2011). "Although it is still unclear whether the CCR7+Foxp3+ Treg cells in the normal salivary glands are natural naïve Treg cells, the decreased cell number in SS patients suggests that the expression of CCR7 on Treg cells may play a key role in the protection of autoimmunity." (PMID 20052419, 2010).
Autoimmunity (continued). "To further evaluate risks of autoimmunity and inflammation, we evaluated the rate of divisions of conventional CD4+ T cells and RAG1-/- cells in vivo, and found no increase in ASO FOXP3 treated group." (PMID 39234236, 2024). "Importantly, the same study was able to identify approximately 300 Foxo1-bound target genes, including IFN-γ, that were not directly regulated by Foxp3, implying that separate and autonomous signaling pathways may operate simultaneously driving Treg function in autoimmunity." (PMID 34539668, 2021). "In the absence of autoimmunity, the phenotype of recipient-derived CD4+ Foxp3+ T cells from CD25cKO mice largely resembled the immature Tregs from their thymus." (PMID 30833563, 2019). "In the context of autoimmunity and inflammation, extracellular IL-33 binds to ST2 directly to promote local expansion, stability, and the conversion of CD4+Foxp3- T cells to Foxp3-expressing inducible Treg cells in non-lymphoid tissues (adipose tissue, skeletal muscle, and colon)." (PMID 35979357, 2022). "Incomplete DT-mediated Foxp3+ Treg depletion in naive adult DEREG mice is advantageous to our studies as it enables a window to study effects of Foxp3+ Treg ablation on myelin reactive CD4+ T cells without confounding complications of lymphoproliferative disease and systemic lethal autoimmunity." (PMID 27708643, 2016). "Other Foxp3− Treg cells include Tr1, Th3, CD8+CD28−/−, and Qa1-restricted T cells; however, the contribution of these Treg cells to self-tolerance, immune homeostasis as well as preventing autoimmunity is not well defined." (PMID 25152867, 2014). "Other Foxp3− suppressor T cells include Tr1, Th3, CD8+CD28−/−, and Qa1-restricted T cells; however, the contribution of these Treg cells to self-tolerance, immune homeostasis as well as preventing autoimmunity is not well defined." (PMID 25152867, 2014). "An absence of PD-1 expression on forkhead box P3 (FOXP3) + CD4+ T cells greatly reduces their ability to suppress the activity of effector T cells, which is essential if self-tolerance is to be maintained and autoimmunity to be prevented." (PMID 24229326, 2013). "Our results suggest that T cells, whether they express CD25 or not, contribute to the development of autoimmunity in this model and this could be due to the fact that both the CD25+ and CD25− cells express similar levels of FoxP3." (PMID 21364747, 2011).
autoimmune disease (538 papers, 2006 to 2026). A disorder resulting from loss of function or tissue destruction of an organ or multiple organs, arising from humoral or cellular immune responses of the individual to their own tissue constituents. "Since Tregs play a crucial role in regulating and maintaining peripheral immunological tolerance, there is active research on the relationship between FOXP3 splice variants and the function of these cells in autoimmune diseases." (PMID 41294856, 2025). "FOXP3 expression is particularly crucial for Treg suppressive activity, as mutations in the FOXP3 gene can lead to severe autoimmune diseases in humans." (PMID 40177538, 2025). "Deletion or mutation of the Foxp3 gene leads to a range of immunological disorders, including allergies, immunopathology, and autoimmune diseases in both mice and humans." (PMID 40183773, 2025). "The polymorphic variants within the Foxp3 gene induce autoimmune diseases, potentially through decreasing the number of functional CD4+CD25+ Tregs." (PMID 39935826, 2025). "There is ample evidence for suggesting the association between FOXP3-2383 C/T (rs3761549) polymorphism and some autoimmune diseases." (PMID 41346162, 2025). "A potential safety risk when targeting FOXP3 expression in Tregs is the link between FOXP3 loss-of-function mutations and autoimmune disorders in humans." (PMID 39937271, 2025). "Tregs, characterized by CD4, CD25, and the transcription factor Foxp3, play a crucial role in controlling inflammation and reducing autoimmune disease risk." (PMID 41012130, 2025). "Loss of function mutation in the Foxp3 gene (scurfy mice) leads to a fatal autoimmune disease characterized by hyperactive CD4 + T cells, and the animals succumb to death within 4 weeks of age." (PMID 39762647, 2025). "Mutations in FOXP3 can cause a functional loss of Treg cells, leading to a severe autoimmune disease in human and mouse." (PMID 40989999, 2025). "Mutations in the FOXP3 gene cause severe autoimmune diseases, tumor invasion, metastasis, and other catastrophic events such as infection-induced inflammatory storms." (PMID 39144146, 2024). "The mutation of FOXP3 in Tregs can induce a shift towards an autoimmune disease in both mice and humans." (PMID 38398067, 2024). "The genetic inactivating mutation of FoxP3 in IPEX syndrome causes spontaneous severe autoimmune diseases and allergies." (PMID 39000278, 2024). "There is evidence to suggest that the FOXP3 gene’s ‘‘G’’ allele increases the risk of developing an autoimmune disease." (PMID 39117877, 2024). "The critical importance of Tregs in the development of T1D and other autoimmune diseases is underscored by mutations in the forkhead box P3 (FOXP3) gene." (PMID 39451194, 2024). "Altered expression of FOXP3 has been observed in many autoimmune diseases and cancer types, including TC, with rs3761548 FOXP3 polymorphism mainly associated with several studied cancer types." (PMID 39000267, 2024). "Diverse single-nucleotide variants have been detected in the FOXP3 promoter region; these variants affect FOXP3 expression while impairing Treg differentiation and function, further affecting the occurrence and development of autoimmune diseases." (PMID 38584670, 2024). "Foxp3 mutation can hinder the development and normal function of Treg cells, resulting in the development of immune dysregulation and autoimmune diseases." (PMID 37795866, 2023). "Mutations of Foxp3 gene can hinder the development of Tregs and lead to a fatal multi-organ autoimmune disease which is called X-linked polyendocrinopathy enteropathy with immune dysregulation syndrome." (PMID 38129374, 2023). "Germline CTLA-4 deficiency causes severe autoimmune diseases characterized by dysregulation of Foxp3+ Tregs, hyper-activation of effector memory T cells, and variable forms autoimmune cytopenia including gradual loss of B cells." (PMID 36909522, 2023).
autoimmune disease (continued). "Regulatory T Cell DefectsIPEX syndrome is an X-linked autoimmune disease caused by mutations in forkhead box P3 (FOXP3) gene." (PMID 37033173, 2023). "Two promoter (−2383/rs3761549 (C>T)) and intronic (IVS9+459/rs2280883 (T>C)) polymorphisms of Foxp3 have been reported to be associated with autoimmune disease risk." (PMID 37998578, 2023). "Recent studies showed that single‐nucleotide polymorphisms (SNPs) in the FoxP3 gene were associated with the increased susceptibility to several autoimmune diseases." (PMID 37904681, 2023). "Deletion of CTLA-4 in mice impairs Tregs’ suppressive function, causing severe autoimmune disease and early lethality, despite normal Foxp3 levels." (PMID 36911741, 2023). "It is evident that loss or gain of Foxp3 also minimizes or maximizes the immunosuppression function of Tregs, which ultimately attenuates severe autoimmune diseases or tumor development." (PMID 37936703, 2023). "Loss of Foxp3 expression is linked with the pathogenesis of multiple autoimmune diseases, including type 1 diabetes in NOD mice." (PMID 37936703, 2023). "Foxp3 is a master regulator of regulatory T cells (Tregs) and its mutations result in fatal autoimmune disease in mice and human." (PMID 38127423, 2023). "Fork head box P3 (Foxp3) gene expression has been observed to be associated with the development of autoimmune diseases and has a suppressive role in the organized immune response against cancer cells." (PMID 37345061, 2023). "Given the importance of FOXP3 in the development, maintenance and function of Tregs, and its strong association with autoimmune diseases we investigated this further." (PMID 37261960, 2023). "Malfunctioning of transcription factor Foxp3 caused by the mutagenesis process affects the development of disorders of the immune response and autoimmune diseases." (PMID 35207219, 2022). "Our study also shows that there is a significant association between reduced FOXP3 gene expression and a positive family history of autoimmune disease (p = 0.03)." (PMID 35266286, 2022). "Similar to that in TGF-β1–deficiency mouse, T cell–specific mutation or deficiency of Foxp3 results in lethal autoimmune diseases early in the life, whereas conditional knockout of Foxp3 in CD4+ T cells causes severe lymphoproliferative diseases." (PMID 36581209, 2022). "FOXP3 was originally identified for its mutation that caused lethal autoimmune diseases in mice and humans." (PMID 36235242, 2022). "Posttranslational modifications (PTMs) are key molecules involved in Th17/Treg differentiation and function (Foxp3, RORγt, and STATs), regulate the Th17/Treg balance, and initiate autoimmune diseases caused by dysregulation of the Th17/Treg balance." (PMID 35935991, 2022). "Mutations in Foxp3 lead to autoimmune diseases, and defects in Foxp3 lead to intestinal mucosal inflammation." (PMID 35075366, 2022). "Regulatory T cell function is mediated by expression of the Foxhead Box Protein 3 (FOXP3) transcription factor (TF) as evidenced by severe autoimmune diseases observed in FOXP3-deficient scurfy mice and IPEX in humans." (PMID 35773720, 2022). "The studies conducted so far indicate the presence of 63 identified mutations within the FOXP3 gene which affect its proper functioning and contribute to the development of autoimmune diseases." (PMID 35207219, 2022). "For instance, FOXP3 regulates the growth and activity of Treg cells, and its deletion or malfunction cause severe autoimmune diseases and inflammatory bowel disease." (PMID 35812386, 2022). "Previous studies have reported that RORγt or STAT3 deficient mice are resistant to autoimmune diseases, and mice treated with FoxP3 displayed enhance Treg function and the alleviation of autoimmune diseases, such as IBD and experimental arthritis." (PMID 35185872, 2022). "miR-31 is among the better studied miRNAs that target FOXP3 and has been implicated in numerous autoimmune diseases." (PMID 36032083, 2022).